CD4 (CD4 molecule)
Diseases named in the same sentence as CD4 in open-access papers (continued):
Sharing a sentence is not in itself a finding about the gene and the disease.
tumor (continued). "Within the TIME, epigenetic modifications can also be found in tumor-associated immune cells, including myeloid cells, CD4+ T cells, and CD8+ T cells." (PMID 33868269, 2021). "Tumor-infiltrating CD4+ T cells upregulated PD-1, cytotoxic T-lymphocyte-associated protein-4 (CTLA-4), T cell immunoglobulin and mucin domain-3 (TIM-3) and LAG-3." (PMID 34660608, 2021). "A well-known subpopulation are CD4+ FoxP3+ T cells or Tregs which are associated with hosting an immunosuppressive environment, promotion of tumor survival and progression." (PMID 33916646, 2021). "There are conflicting literature data on the decrease in the proportion of CD4+T lymphocytes in the blood as a result of tumor invasion, causing CD4+ cells to migrate from the blood to the tumor site." (PMID 34054956, 2021). "In general, CD8+ cytotoxic T cells, CD4+ T-helper 1 cells producing interferon-γ, and natural killer cells are associated with favorable anti-tumor immune responses." (PMID 34787568, 2021). "The mechanism was associated with increased frequency of tumor infiltrating CD3+/CD4+ T cells and DX5+ NK cells." (PMID 33854892, 2021). "The CD8+ and CD4+ T cells, dendritic cells (DCs), regulatory T cells (Treg), and tumor-associated macrophages (TAMs) are mainly present in TME." (PMID 35127473, 2021). "M0 macrophages and resting memory CD4+ T cells were the main components of the tumor immune infiltrate in patients at both high and low risk." (PMID 34497605, 2021). "Regarding CRC, MCP-2/CCL8 derived from cancer-associated fibroblasts have been shown to stimulate the proliferation of cancer cells, while MCP-2/CCL8 and MCP-3/CCL7 derived from tumor-associated macrophages attract anti-tumor CD4+ and CD8+ T cells." (PMID 34884259, 2021). "Another case report study referred about the efficacy of ACT using CD4 T cells directed against the mutated ERBB2 protein expressed by the tumor cells in a patient with a metastatic epithelial cancer, mediating a successful tumor regression." (PMID 34064410, 2021). "Persistently activated STAT3 in tumor-associated B cells, CD4+ and CD8+ T cells upregulates expression of immunosuppressive factors while inhibiting immuno-stimulating molecules." (PMID 34956861, 2021). "In terms of mechanisms, the Th1 immune responses, including those mediated by cytotoxic CD8+ and CD4+ Th1 T cells, along with their characteristic Th1-associated cytokines, function as the major anti-tumor immune pathways restricting disease progression." (PMID 34930302, 2021). "In particular, CD4+ responses to anti-PD-1 were critical in the setting of MHC-I deficient tumor models where MHC-II expression remained intact." (PMID 34068762, 2021). "The presence of heavy infiltration of tumor-infiltrating lymphocytes (TILs) in tumors, particularly CD4+ and CD8+ T cells, was linked to a favorable clinical prognosis for patients, as seen by prolonged progression-free survival (PFS) and OS." (PMID 34680577, 2021). "The transfer type -deficient tumor-reactive CD4+ T cells in Lewis Lung Carcinoma-bearing mice, resulted in a decreased survival rate." (PMID 34262562, 2021). "Suppression of tumor-specific CD4+ T cells by Treg was associated with a worse CRC prognosis in a cohort of 62 patients." (PMID 34204621, 2021). "Tumor-specific mutated antigens resemble foreign proteins and therefore seem to be ideal targets, especially for CD4+ T cells." (PMID 33546283, 2021). "Previous studies have shown that tumor metastasis is associated with the presence of CD4+ T cells and B cells." (PMID 34956309, 2021). "Previous studies have demonstrated that depletion of CD4+ cells is associated with increase in effector function, tumor reactivity, and intratumoral infiltration of CD8+ T cells." (PMID 34493727, 2021). "CAFs were associated with tumor proliferation, elevated memory CD4+T cells and high CD274 (encoding PD-L1) expression." (PMID 34408230, 2021).
tumor (continued). "Regarding CD4 T cells, IFN-α is associated with enhanced activation of CD4+ T cells as well as a reduced frequency of Tregs within the tumor microenvironment." (PMID 33498483, 2021). "Next, the authors co-analyzed scRNAseq and pathologic review, and identified that tissue-resident CD8+ T cells, as well as CD4+ T cells and NK cells, were heavily infiltrated in tumor regions associated with tumor regression or CR to ICI." (PMID 34831009, 2021). "The enhanced persistence of Cbx3/HP1γ-deficient CD8+ T cells facilitates remodeling of the tumor chemokine/receptor landscape ensuring their optimal invasion at the expense of CD4+ Tregs." (PMID 34721405, 2021). "Most of peptide‐based vaccines are based on epitope peptides stimulating CD8+ T cells or CD4+ T helper cells to target tumour‐associated antigens (TAAs) or tumour‐specific antigens (TSAs)." (PMID 33754407, 2021). "Substantial reductions in suppressive cytokines, including CCL2, CCL17, CCL22 and IL-10, were also noted and were associated with reduced CD4+ CD25+ Foxp3+ Treg recruitment in the tumour." (PMID 33513866, 2021). "The processed outputs from this algorithm demonstrated a sharp influx of TILs in the vicinity of malignant TOX+CD4+ T cells that was associated with the progression from the plaque to tumor stage." (PMID 34885092, 2021). "Kreiter and co-workers demonstrated that the majority of tumor-specific mutations (the “mutanome”) is recognized by CD4+ T cells which confer strong antitumor activity." (PMID 33722265, 2021). "Tumour associated macrophages (TAMs) comprised 14.3% (+/- 1.6%) of all viable cells, while tumour infiltrating lymphocytes (TILs) were scarce; CD4+ and CD8+ TILs accounted for 1.4% (+/- 0.7%) and 1.8% (+/- 0.2%), respectively." (PMID 34242269, 2021). "AQP9 had significant association with various immune infiltrating cells including CD8+ and CD4+ T cells, neutrophils, tumor associated macrophages (TAMs) and dendritic cells (DCs)." (PMID 34012923, 2021). "Collectively, our results provide evidence that serum CD4 is associated with the infiltration of CD4+T cells in the tumor microenvironment, which indicates the prognostic value of systemic inflammation in GC." (PMID 34258299, 2021). "The flow cytometry analysis showed significant increases in the ratio of M1:M2 tumor-associated macrophages, meanwhile the number of CD4+, CD8+, CD4+CD69+ and CD8+CD69+ lymphocytes were increased after SCH772984 treatment." (PMID 33816301, 2021). "IHC analysis showed a positive association between IRF3 and IRF7 expression and tumor-infiltrating immune cells, including CD4+ T cell and CD68+ macrophages." (PMID 34488791, 2021). "In the context of IBD-associated cancer, studies in the AOM/DSS mouse model have shown that ablation of CD4+Foxp3+ Treg cells suppressed tumor growth, which was associated with increased numbers of CD8+IFN-γ+ Granzyme B-producing effector T cells." (PMID 34884543, 2021). "This leads to a significant inhibition in tumor growth and increased survival, associated with elevated T cell tumor infiltration and decreased CD4(+) Foxp3(+) T cells." (PMID 34360879, 2021). "Depletion of CD4+ T cells was associated with reduced number of circulating tumor cells and pulmonary metastasis." (PMID 33235291, 2021). "FACS indicated significant changes in the immune environment including a decrease in immune suppressive CD4+ T regulatory cells and increases in tumour-associated GZB+ NK+ cells, which correlated well with tumour radiopharmaceutical uptake." (PMID 35936114, 2021). "Naturally occurring CD4+ T cells directed at tumor-associated or -specific antigens can be detected in the blood of cancer patients, but the impact of these T cell responses on clinical outcome is just starting to be investigated." (PMID 33546283, 2021). "Treatment with soluble GITR ligand (GITRL) reduced inhibition caused by activated tumor infiltrating Treg and restored CD4+ CD25-T cell proliferation and cytokine production." (PMID 34869376, 2021).
tumor (continued). "Our results show that knockdown of PBRM1 in tumor cells causes the reduction of CD4 T cells in the tumor microenvironment." (PMID 34447697, 2021). "High pre-treatment CD8 + T-cell density, high CD4 + T-cell density and low Myeloid-Derived Suppressor Cell density is associated with a higher likelihood of tumour regression and achieving a pCR." (PMID 34302062, 2021). "In the same experimental setup with additional diet-induced steatohepatitis, however, immunotherapy led to progressive tumor growth and a loss of CD4 T cells from the liver." (PMID 34209393, 2021). "The agonist anti-TNFRSF4 antibody is used to inhibit metastasis of metastatic cutaneous squamous cell carcinoma (mSCC) by significantly inhibiting Tregs and by improving the infiltration of tumor-associated CD4+ T cells." (PMID 34367975, 2021). "The tumor microenvironment (TME) in ALK-rearranged caners includes interaction of tumor-associated macrophages (TAMs), CD4+ T cells, CD8+ T cells, regulatory T cells (FOXP3+) and mast cells." (PMID 33806977, 2021). "In the tumor microenvironment, IL-6 are mostly secreted by tumor cells as well as tumor-associated macrophages (TAMs), CD4 + T cells, myeloid-derived suppressor cells (MDSCs) and fibroblasts which directly supports tumorigenesis." (PMID 33407508, 2021). "The low-risk group had a higher proportion of anti-tumor immune cells, including activated CD4+ T cells, activated CD8+ T cells, and natural killer (NK) cells." (PMID 34993138, 2021). "Conversely, tumor-associated FoxP3+CD4+ T cells (regulatory T cells) that induce immunosuppression and promote tumor progression and metastasis were concomitantly reduced." (PMID 33491667, 2021). "Our results showed that the risk score was negatively correlated with 6 tumor-infiltrating immune cell subtypes (B-cells, CD4+T-cells, CD8+T-cells, macrophages, neutrophils, and dendritic cells; p < 0.05)." (PMID 34268304, 2021). "With reference to PD-1 expression within lymphocyte subsets, slight differences in response to anti-PD-1 blockage seem to be associated with differential expression of PD-1 in tumor-associated lymphocytes, predominantly in CD4+ T cells." (PMID 34440813, 2021). "CD4+ T cell effectors can activate M1 tumor-associated macrophages (TAMs) to produce nitric oxide (NO), or partner with natural killer (NK) cells." (PMID 33546283, 2021). "In keeping with other tumour types, high CD4 and CD8 infiltration is associated with improved DFS in PDAC and increased expression of CD163 macrophages is adversely prognostic." (PMID 33481339, 2021). "Patients with high-risk scores had higher proportions of activated memory CD4 T cells, M0 macrophages, M1 macrophages, and mast cells, confirming the roles of ferroptosis-related lncRNAs in the regulation of tumor immune infiltration." (PMID 34312372, 2021). "A variety of immune cells that are closely associated with the reshaping of the TME were detected by flow cytometry, including MDSCs, NKs, Tregs, tumor-associated macrophages (TAMs), dendritic cells (DCs), CD4+ T cells, and CD8+ T cells." (PMID 33867859, 2021). "Increased suppressive activity of MDSCs is associated with increased level of CD4+/CD25+/FoxP3+ Treg cells in the tumor environment." (PMID 34070449, 2021). "Future studies will be needed to standardize the assessment of intrafollicular CD4 + expression and validate the prognostic value of the BioFLIPI risk model alone and in combination with tumor genetic features in independent patient cohorts." (PMID 34267181, 2021). "TME is composed of several cell lines besides cancer cells, including tumor-associated macrophages, cancer-associated fibroblasts, CD4+ and CD8+ lymphocytes, and innate immunity cells." (PMID 34070750, 2021). "CLEC10A recognizes and acts on tumour‐associated Tn antigens and effectively presents the antigens to CD4 T cells." (PMID 33655701, 2021).
tumor (continued). "Of the T cell subsets, the CD4 T cells were the most strongly and significantly associated with the development of tumours, the number of tumours and tumour size." (PMID 34408183, 2021). "CRC patients with high risk scores were more positively associated with tumor-infiltrating immune cells, such as cancer-associated fibroblasts, endothelial cells, M0/1/2 macrophages, and CD4+ T cells." (PMID 33910576, 2021). "In murine models, anti-inflammatory drugs have been associated with a more important CD4/CD8 T-cell infiltration in spleen after tumor rejection." (PMID 35116038, 2021). "Previous studies have shown that CD4+ T cells and tumor-associated macrophages (TAMs) play a central role in pro-tumor immunity; their interactions with tumor cells can directly promote tumor growth, progression, invasion, and metastasis." (PMID 34093661, 2021). "Studies utilizing TLR9 agonists as immune adjuvants in cancer vaccines comprising of tumor-associated antigens showed strong clinical induction of antitumor CD4+ and CD8+ T cells." (PMID 35008305, 2021). "The number of CD8+ T cells, CD4+ T cells, macrophages, and tumor-associated fibroblasts in TME is associated with the clinical outcome of many malignant tumors, such as gastric cancer, urothelial cancer, lung cancer, and breast cancer." (PMID 34712666, 2021). "Activation of TIM3 leads to immune exhaustion of CD8+ T cells and its expression on CD4+ regulatory T cells (Treg) is associated with advanced tumor stage." (PMID 33805268, 2021). "Such clones are much more predominant in the CD8-positive compared to the CD4-positive T-cell compartment, and they are frequently associated with responses to common viral infections and neoplasms." (PMID 33673033, 2021). "For example, interleukin‐2‐mediated STAT3 activity expands tumour‐associated regulatory T cells and enhances Foxp3 expression in CD4+ T cells." (PMID 34449972, 2021). "Using scRNASeq of TILs from LUAD, we found that LAIR2 was predominantly expressed by tumor-associated CD4+ FoxP3+ Treg cells, the presence of which have widely been associated with negative outcomes in a variety of cancers." (PMID 35008369, 2021). "CYP1B1 was significantly associated with tumor purity (r= −0.197, P = 9.53e−04), B cells (r = 0.164, P= 3.81e−03), CD4 + T cells (r = 0.121, P = 4.43e−02), and dendritic cells (r= 0.119, P = 4.88e−02)." (PMID 34784845, 2021). "Generally, CD8 T cells and Th1-differentiated CD4 T cells function to promote anti-tumor immunity, while Tregs and Th2 T cells are associated with immune evasion." (PMID 34831452, 2021). "They observed a significant delay in tumor growth in mice that received the treatment combination in comparison to those received either treatment alone, and this inhibition was associated with an increase in tumor infiltration of CD4+ and CD8+ T cells." (PMID 34203478, 2021). "Cellular infiltration of CD4+ T cell, dendritic cells, and macrophages would lead to immunosuppressive tumor microenvironment and cause unfavorable prognosis." (PMID 34804946, 2021). "A comparison of frequencies of FoxP3+ cells within the CD4+ T cell subset for tumor associated cells and blood (PBMC) for each patient revealed a significantly higher frequency of FoxP3+ cells in tumor vs. blood for each patient (p = 0.001)." (PMID 34926643, 2021). "From single-cell transcriptomics of TILs, LAIR2 was found to be predominantly expressed by tumor-associated CD4 Treg cells, to which a LAIR2-Treg cell derived signature was adversely prognostic in LUAD." (PMID 35008369, 2021). "TIL are comprised of CD8+ T cells, CD4+ T cells, regulatory T cells, tumor associated macrophages, tumor associated neutrophils, myeloid derived suppressor cells, and natural killer cells, which interact with each other to exert antitumor or protumor effects." (PMID 33727924, 2021). "CTLA-4 was associated with CD3+ and CD4+ T cells and PD-1 expression by tumor cells and stroma (considered separately or as one compartment)." (PMID 34830196, 2021).
tumor (continued). "Our results demonstrated that menopausal status, ER, Ki-67 index, CA153 level, WBC count, PLT, and LDH were associated with the densities of CD3+, CD8+ or CD4+ TILs in the tumor microenvironment." (PMID 33718143, 2021). "The expression of FANCE is inversely proportional to the infiltration of CD4 + T cells and their subsets, tumor-associated macrophages (TAMs), M2 macrophages, but positively co-expressed with M1 macrophages." (PMID 33592580, 2021). "By contrary, MDSCs, tumor-associated macrophages and CD4+ Th2 cells promote tumor formation and growth by inhibiting the anti-cancer immune response." (PMID 35127500, 2021). "It has been shown that Dex-induced severe reduction of CD4+ immune cells was associated with high tumour aggressiveness, more rapid disease progression and shorter survival." (PMID 33670244, 2021). "We found a strong association of tumor-infiltrating CD4+ cells and the expression of CD44s and further evaluated the survival rate of patients with positive or negative samples for each factor." (PMID 34885185, 2021). "Because of their specialized characteristics, cDCs actively capture, internalize, and process the foreign pathogenic Ags and self-non-tumor or tumor-derived Ags and then present to CD4+ and CD8+ T cells via the MHC-II and MHC-I molecules, respectively." (PMID 34078376, 2021). "The results showed that patients’ high risk was positively correlated with tumor-infiltrating immune cells such as CD4+ T cells, macrophage, and cancer-associated fibroblast, whereas negatively correlated with neutrophil." (PMID 34434220, 2021). "Of the nine identified cell populations, three were differentially abundant between the control and HMB supplementation groups: neutrophils, CD4+ T cells, and tumor-associated macrophages." (PMID 34944981, 2021). "Overall, our data suggest that activin-A-mediated lung tumor regression is associated with increased numbers of tumor-infiltrating CD4+ T cells with effector phenotype at the expense of CD4+ T cells with suppressive properties." (PMID 34548096, 2021). "This suggests the existence of a correlation between risk-scores and the tumor immune microenvironment, particularly with CD4+ T cells." (PMID 34631307, 2021). "It has been reported that high stromal infiltration of CD8+ ICs and CD4+ ICs was associated with better overall survival by analyzing 139 nivolumab-treated NSCLC simple tumor tissue specimens." (PMID 34136375, 2021). "Strikingly, we also observed that the depletion of CD4+ T cells selectively improves tumor control in Arg2-deficient mice." (PMID 34037806, 2021). "In particular, the treatment with tumor-associated ExVs inhibited maturation and migration of DCs, promoted immune suppression of DCs, decreased CD4+IFN-γ+Th1 cell differentiation and increased the presence of Tregs." (PMID 33435564, 2021). "Compared with the low-risk group, tumor-infiltrating immune cells showed a higher proportion, including M0 macrophages, neutrophils, resting NK cells, and activated memory CD4 T cells." (PMID 34419075, 2021). "As reported, TNFR2 is highly expressed by CD4+Foxp3+ Tregs and is associated with the immunosuppressive activity of tumor-infiltrating Tregs." (PMID 34900985, 2021). "CD4 T lymphocytes evolving in a tumor environment rich in IL-2 (in association with TGFβ) express the transcription factor Foxp3, which impairs the differentiation of Tregs and the production of IL-10, that participate in an immunosuppressive microenvironment." (PMID 33498483, 2021). "Consistently, it is found that the higher density of CD8+ and CD4+ T cells in the central tumor region was linked to longer OS." (PMID 34631551, 2021). "Systemic loss of miR-21 favored tumor progression with weakened CD4 and CD8 T cell antitumor responses characterized by impaired T cell proliferation and decreased IFN-γ and IL-2 secretion." (PMID 34830805, 2021).